BRAF (B-Raf proto-oncogene, serine/threonine kinase)
Diseases named in the same sentence as BRAF in open-access papers (continued):
Sharing a sentence is not in itself a finding about the gene and the disease.
melanoma (continued). "Emerging resistance mechanisms to targeted treatment may influence response to subsequent ICI, particularly in BRAF mutant melanoma." (PMID 40362630, 2025). "For example, the gene BRAF, which carries an activating mutation in about 50% of melanoma, occurs as a splice variant lacking exon 4–8, resulting in a loss of the RAS‐binding domain and therefore resistance against respective inhibitors." (PMID 39212334, 2025). "However, the development of dysplastic nevi and new primary melanoma within pre-existing moles in patients treated with other BRAF inhibitor monotherapy has been rarely reported." (PMID 39839461, 2025). "However, it has been shown that the reducing expression of SOX10 or the depletion of its target SAMMSON increases the sensitivity of BRAF-mutant melanoma to MAPK inhibitors, suggesting that upregulation of SOX10 promotes resistance to inhibitor therapy." (PMID 40872623, 2025). "Olaparib is a PARP inhibitor, and emerging evidence suggests that combining Olaparib with BRAF and MEK inhibitors may benefit melanoma patients with BRAF mutations." (PMID 40297440, 2025). "This suggests that therapies targeting GPX4 could be particularly effective in melanomas resistant to apoptosis-inducing therapies, such as BRAF and MEK inhibitors." (PMID 40427437, 2025). "Malignant melanoma treatment often involves surgical excision with clear margins, adjuvant therapies such as immunotherapy (e.g., checkpoint inhibitors), targeted therapy (e.g., BRAF inhibitors), and in some cases, radiation and chemotherapy." (PMID 40851874, 2025). "We have previously demonstrated that the treatment of mice bearing genetically derived inducible melanoma tumors (BRAF/PTEN or NRAS/INK4a) with the CXCR1/2 antagonist (SX-682) inhibited tumor growth and increased activated CD8+ T cells, partly by reducing the intratumoral MDSCs." (PMID 40904502, 2025). "Moreover, the combination of BRAF inhibitors and MEK inhibitors with ICIs for BRAF-mutant melanomas has proven effective." (PMID 40746887, 2025). "The inhibition of OXPHOS can also be applicable in BRAFi-resistant cells and to prevent BRAF-mutant melanoma brain metastasis, which suggests that the metabolic phenotype of melanoma cells can be switched during the acquisition of drug resistance and metastatic potential." (PMID 39970778, 2025). "Therefore, it is plausible that the siRNA used in our study induced apoptosis in A375 melanoma cells through mechanisms unrelated to BRAF inhibition." (PMID 41170188, 2025). "Clinical effects of BRAF plus MEK inhibitors are limited by drug-tolerant cells in melanoma." (PMID 40955663, 2025). "For example, BRAF and NRAS mutations are prevalent in superficial spreading and nodular melanomas, NF1 loss is associated with chronic sun-damaged melanomas, KIT mutations are more common in acral and mucosal disease, and GNAQ/GNA11 mutations characterize uveal melanoma." (PMID 41283484, 2025). "The prognosis for melanoma remains poor, highlighting the urgent need for more precise biomarker identification and aggressive therapeutic strategies to improve clinical outcomes, especially in BRAF wild-type melanoma." (PMID 40809015, 2025). "A limitation of this model is that it does not fully represent the biology of all melanoma patients with established brain metastases, as this model is driven by mutant BRAF in the context of Akt1E17K along with Pten and Cdkn2a loss." (PMID 40944916, 2025). "Similar principles apply to BRAF-mutant melanoma treated with BRAF inhibitors." (PMID 41614813, 2025). "The BRAF mutational status is less important in patients with stage 0 and stage I melanomas because these patients typically do not undergo systemic therapy." (PMID 41010758, 2025).
melanoma (continued). "Our analysis reveals three core insights: First, biomarker mechanisms are now well-defined across species, with diagnostic tools like CRP in canine sepsis, prognostic indicators such as cfDNA in oncology, and predictive signatures like BRAF in melanoma enabling more targeted interventions." (PMID 41227463, 2025). "With advancements in targeted therapies, the combination of BRAF and MEK inhibitors has demonstrated prolonged survival and delayed resistance in patients with BRAF mutations, while immune checkpoint inhibitors have shown effectiveness across both BRAF-mutant and wild-type melanoma cases." (PMID 40002300, 2025). "Two BRAF V600E selective inhibitors vemurafenib (clinical Cmax 127 μM) and dabrafenib (clinical Cmax 4.86 μM) were tested in combination with ipatasertib in two BRAF V600E mutant colon carcinoma lines, 616215-338-R-J1 and 817829-284-R-J1, and in a single BRAF V600E mutant melanoma line, MALME-3M." (PMID 40761343, 2025). "The melanoma tumour-specific factors encompassed BRAF status and serum S100 concentrations." (PMID 40227712, 2025). "The remaining melanomas can be described as triple-negative (triple-wild-type: BRAF, RAS, KIT)." (PMID 40361349, 2025). "The effect of BRAF mutation on the response to anti‐PD1 therefore may be considered when choosing between adjuvant anti‐PD1 and BRAFi/MEKi for patients with BRAF V600 mutant melanoma." (PMID 41342263, 2025). "We found that melanoma induces autophagy regardless of BRAF mutation when treated with Dabrafenib or Dacarbazine." (PMID 41155168, 2025). "In co-culture with two melanoma cell lines, ME4405 and SK-MEL-28 (which harbor BRAF and NRAS mutations, respectively), we observed that knockdown of CCNB1 in melanoma cells increased the proportion of NK-92MI expressing CD69 and CD107a, which are key markers of NK cell activation." (PMID 40430484, 2025). "Targeted therapies against BRAF and NRAS mutations have been recently explored in melanomas." (PMID 41394861, 2025). "Furthermore, AR antagonists improve the response to BRAF/MEK-targeted therapy in preclinical models of melanoma." (PMID 39837817, 2025). "To test this hypothesis, we first treated LM2, MDA-MB-231 (from which LM2 cells are derived), and A375p melanoma cells (which harbour activated mutant BRAF) with the MEKi Binimetinib." (PMID 40353692, 2025). "Furthermore, they suggest an opportunity for RAC1 pathway targeting agents in resistance-breaking combination approaches for BRAF-mutant melanoma." (PMID 39636745, 2025). "Therefore, we underline the association of BRAF- and NRAS-mutated melanomas with clinicopathologic features underlying a more aggressive melanoma phenotype." (PMID 40867317, 2025). "The combination of BRAF plus MEK inhibitors (dabrafenib plus trametinib) is licenced in the adjuvant setting only for patients with resected BRAF V600E or BRAF V600K mutant Stage III melanoma, based on the results of the COMBI-AD trial." (PMID 39859464, 2025). "This melanoma had a Breslow thickness of 1.2 mm and stained positively for BRAF V600E." (PMID 40851494, 2025). "In vitro studies show that Lmat-LLO causes ROS generation and apoptotic cell death in numerous melanoma cell types, independent of stage, mutational profile, susceptibility to BRAF inhibitors, or stemness." (PMID 40519767, 2025). "Additionally, in one study, BRAF V600 mutant melanoma patients treated with vemurafenib, another BRAFi, were assessed of ctDNA plasma concentration using a ddPCR targeting the BRAF V600E/K mutation." (PMID 39859576, 2025). "For BRAF-WT melanoma, approved second-line options are very limited." (PMID 39550033, 2025). "While this mutation is a strong driver of melanoma proliferation, our findings demonstrate that modulating CLEC4A expression still significantly impacted proliferation, migration, and invasion in this BRAF-mutant context." (PMID 40607411, 2025).
melanoma (continued). "A further study of 142 advanced melanoma patients (70 receiving BRAF/MEKi and 72 receiving ICIs) found that baseline ctDNA was detectable in 56% of cases, with declining ctDNA within 12 weeks strongly associated with better outcomes (p < 0.001 for PFS, p < 0.05 for OS)." (PMID 39859576, 2025). "Secondary resistance to BRAF inhibitors in melanoma can be classified into two forms: adaptive resistance, which arises early through reversible cellular reprogramming, and acquired resistance, which develops later through stable genetic or epigenetic alterations." (PMID 40872623, 2025). "Similar to these findings with ALK+ NSCLC cells, it is reported that in DTP cells in EGFR+ NSCLC, HER2+ breast cancer, and BRAF+ melanoma, the gene signatures of ROS production are increased after treatment with clinically relevant TKIs and the expression of antioxidant genes is also decreased." (PMID 39369284, 2025). "Conversely, BRAF mutation was more frequently observed in ulcerated than non-ulcerated melanomas (69.6% and 28.1%; p = 0.003) and in melanomas with mitotic rate ≥ 5 than <2 n/mm2 (72.7% and 22.2%; p = 0.003)." (PMID 40867317, 2025). "Furthermore, the amount of ctDNA shed into the blood depends on the type of tumor, a concept known as tumor-shedding, which influences the ctDNA detection rate; in advanced BRAF-mutant melanoma, it is reported to be around 80%." (PMID 39859576, 2025). "Their mutational pattern showed enrichment in gene involved in oncogenic signaling pathways and in DNA repair, as also found in BRAFV600E melanoma cell lines resistant to BRAF inhibitor in the collection of the Cancer Cell Line Encyclopedia, and in tumors resistant to targeted therapy." (PMID 41550951, 2025). "Targeted siRNA therapy shows potential for silencing BRAF and advancing melanoma treatment." (PMID 41170188, 2025). "Moreover, OPi, a novel OXPHOS complex I inhibitor, showed antitumor activity in MAPKi-resistant BRAF-mutant melanoma by promoting glycolytic metabolism and suppressing the TCA cycle through the LKB1-AMPK axis." (PMID 40617808, 2025). "Moreover, MC1R mutations have a synergistic effect with other melanoma-associated mutations, particularly in CDKN2A and BRAF, further amplifying melanoma risk." (PMID 40507265, 2025). "Inadequacy of testing for melanoma BRAF status results in delayed access to systemic therapy." (PMID 40902091, 2025). "However, most studies included advanced cases of melanomas with a higher Breslow index compared to the current study, because the clinical recommendation for BRAF testing in melanoma is for stages III-IV and should be considered in stages IIB-IIC." (PMID 41010758, 2025). "Although immune checkpoint inhibitors (ICIs) and BRAF/MEK inhibitors have transformed melanoma management and significantly improved patient survival, treating unresectable NAM remains challenging due to the low frequency of BRAF mutations and resistance to immunotherapy." (PMID 40437181, 2025). "Initially, the approval was for BRAF V600E mutations for only a few cancers such as melanoma, non-small cell lung cancer, and anaplastic thyroid cancer but evidence of added efficacy in other cancers led to pan-tumor approval." (PMID 40869231, 2025). "Furthermore, targeting the transcription factors GLI1/GLI2 (nuclear effectors of the Hh pathway) was able to reverse the treatment resistance of melanoma cells refractory to BRAF inhibitors and even prevent the acquisition of resistance to chemotherapy." (PMID 40806546, 2025). "This study presents the largest dataset on national melanoma BRAF status published to date." (PMID 40902091, 2025). "BRAF-mutant melanomas have a significantly higher activation of AKT than NRAS-mutant melanomas." (PMID 40076927, 2025).
melanoma (continued). "Melanoma patients suffering from V600-mutant melanoma showed improved results upon combination therapy (BRAF inhibitor plus MEK inhibitor, e.g., vemurafenib plus cobimetinib, dabrafenib plus trametinib, and encorafenib plus binimetinib) compared with the corresponding BRAF inhibitor monotherapy." (PMID 39935431, 2025). "In the last decade, the clinical management of melanoma has undergone a revolutionary transformation due to the introduction of BRAF and MEK inhibitors alongside advancements in immunotherapy, leading to a substantial enhancement in the overall survival rates of patients." (PMID 40809015, 2025). "In practice, systemic-first strategies are reasonable for asymptomatic, small-volume brain metastases from EGFR/ALK-driven NSCLC or BRAF-mutant melanoma, initiating CNS-active systemic therapy and deferring focal radiotherapy with MRI surveillance every 6–8 weeks." (PMID 41296115, 2025). "The advent of targeted therapies, including BRAFV600E inhibitors such as vemurafenib, dabrafenib, and encorafenib and inhibitors of MEK, including trametinib, cobimetinib, and binimetinib, have markedly improved clinical outcomes for patients with BRAF-mutant melanoma." (PMID 41227355, 2025). "Importantly, the Mitogen Activated Protein Kinase (MAPK) pathway has been identified as a major culprit, with BRAF V600, NRAS Q61 and NF1 mutations driving 60%, 20% and 4% of melanomas, respectively." (PMID 41168392, 2025). "Specifically, identifying whether “BRAF‐high” tissues with suppressed immune signatures originate from superficial spreading melanoma (SSM), nodular melanoma or ALM would significantly enhance interpretability." (PMID 41002140, 2025). "Additionally, we identified targetable fusions, such as KIAA1549::BRAF, which represent therapeutic opportunities for advanced melanoma, including novel type II RAF inhibitors with potent activity against kinase fusions." (PMID 40737104, 2025). "Clinical data support this observation, suggesting that AR activity, and possibly patient sex, may impact outcomes in BRAF-mutant melanoma." (PMID 40332392, 2025). "Two BRAF inhibitors, vemurafenib and dabrafenib, have been approved for the treatment of melanoma." (PMID 40959083, 2025). "However, in murine BRAF-transformed melanocytes, overexpression of MITF inhibits proliferation, indicating that the regulation of MITF expression levels by the MAPK pathway plays an important role in the growth of BRAF-driven melanoma." (PMID 40063190, 2025). "Thus far, PF-07799933 has been well tolerated as both monotherapy and combination therapy for melanoma and elicited tumor reduction in patients who were treated with BRAF inhibitors in the past." (PMID 40564107, 2025). "Over the past few decades, research has primarily focused on defining the genomic landscape of primary melanoma and metastatic disease, uncovering key genetic alterations, such as BRAF, NRAS, AKT1, and PTEN mutations, that shed light on melanoma progression and treatment resistance [3,4,]." (PMID 40669378, 2025). "Mutations in BRAF (rapidly accelerated fibrosarcoma B-type) and NRAS (neuroblastoma RAS viral oncogene homolog) are the most common genetic drivers of melanoma, with BRAFV600E occurring in over 50% of cases and NRAS mutations, such as Q61R, observed in 15−20% of cases." (PMID 40141318, 2025). "The advent of BRAFi and MEKi has significantly improved outcomes in BRAF V600-mutant melanoma." (PMID 40872623, 2025).
melanoma (continued). "Several MAPK pathway inhibitors have been approved by the US Food and Drug Administration (FDA) for the treatment of clinical melanoma, including BRAF and MEK kinase inhibitors, which are poorly tolerated and are prone to development of resistance during treatment." (PMID 40514365, 2025). "•Copper regulates key melanoma signaling pathways e.g., BRAF/MEK/ERK, and pigmentation." (PMID 39970778, 2025). "It is evident that BRAF-mutant melanomas treated with MAPK inhibitors are able to adapt over time." (PMID 40872623, 2025). "Moreover, melanoma consists of distinct molecular subtypes (e.g., BRAF-mutant, NRAS-mutant, triple wild-type), each with unique gene expression profiles." (PMID 40722520, 2025). "In BRAF(V600E)-mutant melanoma cells, dabrafenib was shown to suppress necroptotic signaling pathways, suggesting that activating necroptosis may circumvent resistance mechanisms." (PMID 40909289, 2025). "As Hsp90 inhibitors target client proteins of resistant pathways, we hypothesised that C‐terminal Hsp90 inhibitors will target BRAF/MEK inhibitor resistant melanoma cells by overcoming the resistant pathways." (PMID 40135438, 2025). "Furthermore, advancements in molecular oncology have facilitated the detection of mutations in genes like BRAF, NRAS, and c-KIT in canine melanomas." (PMID 41394861, 2025). "COX-2 inhibition was shown to prevent human melanoma cell proliferation and induce cell death, independent of BRAF or NRAS mutations." (PMID 39941844, 2025). "By contrast, mucosal and other non-cutaneous melanomas have lower rates of BRAF and NRAS mutations and higher frequencies of KIT and other alterations." (PMID 41384184, 2025). "This study provides significant information for the design of future clinical trials for ICI-resistant melanomas without BRAF mutation." (PMID 40904502, 2025). "PD‐1 or BRAF + MEK inhibition is considered the current gold standard in adjuvant melanoma therapy." (PMID 40331873, 2025). "In patients treated with anti‐PD1 monotherapy (n = 76), those with BRAF V600 mutations (n = 9) had a significantly shorter RFS (p < 0.0001) and an increased hazard of recurrence (HR 5.4, CI: 2.2–14.0, p < 0.001) compared to patients with BRAF WT melanomas treated with anti‐PD1 (n = 64)." (PMID 41342263, 2025). "Similarly, melanoma frequently exhibits DTP cells after treatment with BRAF/MEK inhibitors, contributing to adaptive resistance and relapse." (PMID 40894234, 2025). "En un ensayo clínico en fase 2 prospectivo y multicéntrico se analizaron pacientes tratados con encorafenib (inhibidor de BRAF) y binimetinib (inhibidor de MEK) seguidos de radioterapia en pacientes con melanoma positivos para BRAF V600 y con metástasis cerebrales." (PMID 40977817, 2025). "BRAF inhibitors have a 50–70% response rate in melanoma but are less effective for thyroid cancer." (PMID 40869231, 2025). "Moreover, patients with localized BRAF-mutant melanoma have demonstrated poorer DFS compared with those harboring wild-type tumors (HR = 2.2; 95% CI, 1.1–4.3) independent of AJCC staging." (PMID 40981345, 2025). "Clinical trials have demonstrated that combining luminespib with ALK inhibitors in ALK inhibitor-resistant non-small cell lung cancer (NSCLC) improved the clinical response, and that HSP90 inhibitors also restored sensitivity to BRAF/MEK inhibitors in resistant melanoma models." (PMID 40872476, 2025). "Considering TRIM63-dysfunction in melanoma cells carrying BRAF mutant, we speculated that TRIM63 may be associated with BRAF mutation." (PMID 41315179, 2025). "More recently, Glasheen and colleagues showed that melanoma cells with and without BRAF mutations have elevated levels of the cIAP2 protein (the BIRC3 gene product), which mediates tumor cell resistance to MEK inhibitors." (PMID 41465443, 2025).